TNF (tumor necrosis factor)
Diseases named in the same sentence as TNF in open-access papers (continued):
Sharing a sentence is not in itself a finding about the gene and the disease.
infection (continued). "Proinflammatory cytokine TNF-α and lysosomal enzyme HEXB effectively contribute to bactericidal activity at this time point of infection." (PMID 35631117, 2022). "Pro-inflammatory Th1 responses, which mainly involve IFN-γ or TNF-α producing CD4+ T helper cells, and Th17 responses are considered important for protection against infections with extracellular pathogens." (PMID 36569943, 2022). "We recently observed that infection with either attenuated (NH/P68) or virulent (22653/14) ASFV resulted in moMφ impaired ability to release IL-12, IL-6, and TNF-α in response to stimulation with IFNγ and LPS or a TLR2 agonist." (PMID 35215216, 2022). "In response to bacterial infection, interleukin-6 (IL-6), tumor necrosis factor-α (TNF-α), and interleukin-1β (IL-β) induce PCT synthesis in extrathyroidal tissue with a peak at 6 h from the onset of infection and a half-life of 24 h." (PMID 36139922, 2022). "Subsequently, the regulation of the immune response to infection adjusts the expression of inflammatory factors, including iNOS, COX-2, IL-6, IL-1β, and TNF-α." (PMID 35159514, 2022). "Inflammation-related signaling pathways, including RILR, TLR, NLRs, NFκB, Jak-STAT, and TNF, mediated the intestinal epithelial cell (IEC) infection and severe inflammation induced by transmissible infection gastroenteritis virus." (PMID 35795789, 2022). "Some studies have suggested that IL-1β, TNF-α, IL-2, IFN-γ, and IL-6 were markedly upregulated in critical patients after infection with SARS-CoV-2 and thus can be used as biomarkers to determine the severity of disease in patients." (PMID 36069561, 2022). "Since there are presently no recognized and accepted biomarkers for assessing SCI levels alone, SCI is usually measured by combining the clinical biomarkers of acute inflammation and infection, such as CRP, IL-6, and TNF-α." (PMID 36556207, 2022). "Previous studies also demonstrated that the expression of IFNα/β, TNFα, IL-1β, IL-6, and IL-8 in serum, BALF and tracheobronchial lymph node homogenates increased after infection with PRRSV." (PMID 35928151, 2022). "VEGF and TNF-α levels were relatively weak and transient, whereas IL-1Ra, IL-8, and MCP-1 levels were high and were maintained at different time points following infection." (PMID 35603150, 2022). "In contrast, the adjuvanted (VSA-1, QS-21) sCal vaccine groups showed lower levels of inflammatory cytokines (TNF-α, IL-6, IFN-γ, IL-1β) in the lung compared to the naïve mice with infection." (PMID 36146461, 2022). "Bacteria burdens, neutrophil recruitment, and activation (CD11b expression, myeloperoxidase, and elastase levels), interleukin (IL)-1β, IL-6, and tumor necrosis factor (TNF) were measured in bronchoalveolar lavage fluid (BALF) at 6 and 24 h after infection." (PMID 35269409, 2022). "It is stimulated by diverse factors such as the tumor necrosis factor (TNF) superfamily (TNFR1, Fas/CD95, and TRAIL-R), Toll-like receptors (TLR3 and TLR4), interferon-γ (IFN-γ), lipopolysaccharides (LPS), pathogen infection and various drugs." (PMID 36361505, 2022). "Specifically, infection of mice with murine CMV has been shown to increase levels of IL-12, INF-γ, TNF-α, and IL-6." (PMID 35458404, 2022). "PTGER2 was significantly upregulated in both CD4+ (p=0.0039) and CD8+ (p=0.0086) T cells in active infection, as were CD4+ TNF expression (p=0.0364) and CD4+ EGR2 expression (p=0.0069)." (PMID 36439147, 2022). "TNF-α is a pyrogenic cytokine secreted by macrophages, monocytes, Th1 cells, Th17 cells, CD8+ T cells, and DCs during the acute phase of inflammation or infection." (PMID 35464491, 2022). "It triggers multiple signaling pathways to produce tumor necrosis factor (TNF)-α, interferon (IFN)-β, interleukin (IL)-6 and other proinflammatory cytokines to attract immune cells to the site of infection." (PMID 35214602, 2022).
infection (continued). "Since TNF is a major factor in SARS-CoV-2–induced inflammation, we further investigated TNF expression at the site of infection using RNAScope." (PMID 36378534, 2022). "A cascade of biomolecular events occurs in an intricate network after exposure infection of SARS-COV-2 including the production of interleukins 1β, 6, 10 (IL-1β, IL-6, IL-10, MCP-1), and tumor necrosis factor-α (TNF-α)." (PMID 34463916, 2022). "We examine the levels of TNF-α, IL-12, IFN-γ, IL-2, TGF-β, IL-10, IL-17, and IL-6 in lung lysates obtained from M. tb-infected mice at different timepoints post-infection." (PMID 35453358, 2022). "Interestingly, MKN-28 cells infected with ΔhtrA at both 2-h and 6-h time points exhibited increased TNF expression implying that HtrA may be involved in TNF signaling, a view that was supported by the observed deregulation of ZFP36, BCL3 and TNF during infection with the ΔhtrA mutant." (PMID 37193047, 2022). "Upon infection, HRV further exaggerated the secretion of IFNγ (P < 0.01), and enhanced TNFα (another Th1 cytokine) production (P < 0.01) in COPD cultures compared to HRV infected healthy cultures." (PMID 35280870, 2022). "After infection with Aeromonas hydrophila, we found that the IL-10 and IL-11 expression levels were upregulated in each group, while TLR-4, MYD88, and TNF-α were down regulated." (PMID 36139830, 2022). "The expressions of IL-1β, IL-6, TNF-α, IFN-γ, IL-12, and CXCLi1 were also markedly increased in the livers of wild-type infected chickens on 5 days post-infection." (PMID 35694286, 2022). "Treatment with raltegravir from 0 to 2 dpi indeed increased the percentage of cells that expressed GFP after treatment with either PMA or TNF-α, even though the number of GFP+, that is, productive infections detected at 5 dpi was similar." (PMID 36376394, 2022). "Release of the inflammasome-independent cytokine TNF-α was similar across the various THP-1 genotypes and treatments following infection." (PMID 35073381, 2022). "Negative hematological changes including increased inflammatory cytokines such as tumor necrosis factor-alpha (TNF-alpha), interferon-gamma (IFN-γ), and interleukin 6 (IL-6) are prominent in cases with severe infection." (PMID 35627841, 2022). "High levels of TNF-α, IL-6, IFN-γ, and IL-1β cytokines were induced in the lung samples from naïve mice at 6 days after infection." (PMID 36146461, 2022). "We found that the expressions of pro-inflammatory cytokines such as IL-6, IL-1 β, IL-17, TNF-α, and TGF-β were significantly increased after an MP infection." (PMID 35383237, 2022). "Interestingly, polymorphisms in TNF-α and β-cytokine receptors can confer an increased risk of congential CMV infection, suggesting that some fetuses may be particularly susceptible to infection, and potentially explaining how many neonates are unaffected by maternal CMV infection." (PMID 35844234, 2022). "Multiple studies show that those with severe filovirus infections have higher serum levels of proinflammatory biomarkers such as such as IFN-γ, IL-2, IL-8, IL-10, TNF-α, and IFN-α at various points in the infection compared to those with less severe disease." (PMID 36558734, 2022). "NK cells can respond to host infections by recognizing cytokines IL-12 and IL-18 and producing interferon-gamma (IFN-γ) and TNF, as well as excreting perforin and granzymes which penetrate the membrane of an infected cell and induce apoptosis." (PMID 35251030, 2022). "B lymphocytes have also been shown to internalize F. tularensis cells during infection and produce a variety of cytokines, including IFN-γ and tumor necrosis factor (TNF)." (PMID 35275912, 2022). "In general, the BCGΔRS01790 infection group exhibited significantly higher serum levels of IFN-γ, TNF-α, and IL-1β than WT BCG and cBCGΔRS01790::RS01790 groups before 8 dpi." (PMID 35281073, 2022).
infection (continued). "The results showed that at the initial stage of infection, the expression levels of intestinal inflammatory factors such as IL-1β, IL-6, IL-10, TGF-β and TNF-α in the treatment group were much lower than those in the challenge group (p < 0.01)." (PMID 36431853, 2022). "The levels of GM-CSF, IFN-γ, and TNF-α were upregulated at 7 days post-inoculation; this finding was contrary to the results obtained after HLJ/18 or HLJ/18ΔCD2v infection." (PMID 36146810, 2022). "We found cytokines like IFNγ, IL-4, IL-13, IFNβ1, TNFα, and transcriptional regulators such as HIF1α, STAT1, CTCF, TP73, IRF1, MXD1, ATF4, SPI1 mediate macrophage activation upon infection." (PMID 35789215, 2022). "After infection with SARS-COV-2, the innate immune system is triggered, and various inflammatory pathways are activated, among which NLRP/IL-1β, JAK/STAT, TNF-α/NF-κB, and other pathways have been confirmed to be closely related to SARS-CoV-2 infection." (PMID 36278166, 2022). "We assessed the relative frequencies of TNF-α-, IFN-γ-, and IL-17-producing Vδ1+ and Vδ2+ T cells at the time of infection." (PMID 36359845, 2022). "Human neutrophils also produce numerous different pro- and anti-inflammatory cytokines upon stimulation, such as TNF-α, IL-1β, IL-6 and IFN-γ, as well as a wide array of chemokines to recruit other immune cells to the site of infection." (PMID 36203565, 2022). "Some previous reports assessed the safety of anti-TNF treatment for elderly patients with IBD and demonstrated that older age was the only independent factor for SAEs, including infection, malignancy, and cardiovascular and death events." (PMID 35351986, 2022). "At 24 hr post-infection, the mRNA level of TNF-α (I) and concentration of TNF-α in the culture supernatant of JEG-3 cells (J) (n=3) were determined by RT-qPCR and enzyme-linked immunosorbent assay (ELISA), respectively." (PMID 35972780, 2022). "However, upregulation of TNF may have an impact on NF-κB signaling by enhancing its nuclear translocation, which is key for NF-κB-mediated transcription of genes necessary to combat infection." (PMID 35844510, 2022). "CD4+ T cells are crucial in the whole-body resistance to HAV infection, and they produce a large number of cytokines in the early stages of infection, including IFN-γ, TNF-α, IL-2, and IL-21." (PMID 36248427, 2022). "TrpRS is secreted into the extracellular milieu by monocytes upon infection with certain pathogens and it interacts with TLR2 and TLR4 leading to the secretion of TNFα, neutrophil infiltration, and increased phagocytotic abilities." (PMID 35634293, 2022). "The infection cytokines produced by interleukin (IL-6, IL-8, IL-1β), tumor necrosis factor-alpha (TNF-α), and interferon-gamma (IFN-γ) are all accompanied by a severe infection." (PMID 36421668, 2022). "It is mostly produced by macrophages, monocytes, and fibroblasts induced by TNF-α, INF- α, INF- β, and INF- γ and acts in the early infection response." (PMID 35269619, 2022). "HLJ/18-7GD further upregulated the levels of GM-CSF, IFN-γ, and TNF-α at 7 DPI, which was in contrast to the results obtained after HLJ/18 or HLJ/18ΔCD2v infection." (PMID 36146810, 2022). "With increasing severity of the infection, higher levels of circulating cytokines and other inflammatory biomarkers like IL6, IL-1β, TNFα, C-reactive protein (CRP) and D-dimer occurs." (PMID 36590303, 2022). "IL-6, IL-8, IL-1β, TNF-α, and IFN-γ are pro-inflammatory cytokines involved in promoting the acute inflammatory response and defending against infection." (PMID 36364088, 2022). "Our data strongly suggest that CTL responses correlate with protection against PRRSV-1 transplacental infection, being executed by CD4 T cells (IFN-γ related) and/or CD4/CD8α DN T cells (TNF-α related)." (PMID 36798517, 2022).
infection (continued). "Our results indicate that infection with WT GBS results in significantly enhanced production of IL-1β, KC, and TNF-α in the uterus, decidua, placenta, amnion, and fetus compared to uninfected controls (*P < 0.05, one-way ANOVA, #P < 0.05, Student’s t test)." (PMID 36104331, 2022). "Several pro-inflammatory cytokines, such as TNF-α, IFN-g, TGF-b, and IL-10, were triggered in response to bacteria after infection." (PMID 35369604, 2022). "Both infection-induced MDM1 and MDM2 populations have high signature scores for pro-inflammatory pathways such as an INFγ response, TNFα signaling via NF-kB, and general inflammatory responses." (PMID 36420267, 2022). "ELISA assay revealed consistent results with the qRT-PCR assay, suggesting that dTHP1 cells secreted large amounts of proinflammatory cytokines (IL-6, IL-1β, and TNF-α) and chemokine MCP-1 into the supernatant during the infection process (p < 0.05)." (PMID 35359716, 2022). "For example, to establish an infection, DENV requires T helper 1 (TH1) responses which stimulate the production of interleukin-12 (IL-12), interleukin-18 (IL-18), tumor necrosis factor (TNF), and IFN-γ." (PMID 36189361, 2022). "In the primary infection, the mRNA levels of cytokines and chemokines including RANTES, IFN-α, MIP-1-α, IFN-γ, IL-6, IP-10, TNF-α, and IL-1-β were increased in the nasal mucosa and lung, except IL-1-β, which was not increased in the lung." (PMID 35893674, 2022). "SAA production is regulated by IL-1, IL-6, and TNF, and SAA is released in response to infection and injury." (PMID 35449688, 2022). "We noted moderately elevated levels of IL-1β, TNF-α, and IFN-γ in C3ar-/- lungs at 6 days post-infection." (PMID 36174103, 2022). "TNF-α, IL-6, and INF-γ’s Levels in the serum of MafK Tg mice were all significantly upregulated compared to WT mice following a 2 day infection with Salmonella." (PMID 35260530, 2022). "It acts on early host response to infection, precedes increases in CRP, and is observed after tumor necrosis factor alpha (TNFα) has been released." (PMID 34846061, 2022). "Endothelial cells expressed IFN-β, IL-7, TNF, CCL2, and common inflammatory markers such as ICAM1 and VCAM1 after infection with IAV H5N1 as compared to the H1N1 virus." (PMID 36071442, 2022). "TNFα is a major regulator of immunological processes and has been reported in RSV as a mediator in infection-related illness." (PMID 36405747, 2022). "Immunized mice showed an early, yet discrete, increase in IL-6 and TNF-α in BAL fluids, while the control group had a delayed response upon infection." (PMID 36477013, 2022). "The phenotype of M1 macrophages is activated by infection and pro-inflammatory Th1 cytokines, including bacterial lipopolysaccharide (LPS), interferon-gamma (IFN-γ), and tumor necrosis factor-α (TNF-α)." (PMID 36429021, 2022). "For example, exposure to cytokines such as TNF-α, IL-1β, IFN-γ and GM-CSF, can drive neutrophil activation as well as amplify neutrophil recruitment to the site of infection." (PMID 36203565, 2022). "Macrophages also synthesize and secrete several cytokines like IL-1 and Tumor necrosis factor (TNF), which play role in the training and activation of CD4 helper T-cells for the recognition and destruction of a pathogen to resolve different infections." (PMID 36619389, 2022). "This was the case for the type I IFN response, but also for RIPK1, STAT1, DDX58, ISG15, TRIM25, and MYD88, involved in TNF-, TLR-, RLR-, and NFκB signaling, 48 h after MOPV infection." (PMID 35337059, 2022). "A significant increase in gene expression of TNF-α and TGF-β was observed in HCV infected cells in presence of P2X4 on day 9 post infection in comparison with control (NV/HCV cells)." (PMID 35594248, 2022). "To further investigate effects of knocking out RIOK3 on inflammatory cytokine expression stimulated by TNFα treatment and RVFV MP12 infection, we employed a luciferase reporter construct (p NFκB-Luc) that is specifically driven by activated NFκB." (PMID 36146870, 2022).
infection (continued). "We analyzed the secretion or expression of different immunomediators (cytokines CCL2, CXCL8, TNF-α, and interferon-stimulated gene ISG15) at different times following infection of PAMS." (PMID 35019713, 2022). "Compared with patients diagnosed with IVA or IVB infection, HMPV-positive patients had significantly higher levels of IL-4 (p < 0.001 and < 0.001), IFN-γ (p < 0.001 and < 0.001), and TNF-α (p < 0.001 and 0.016)." (PMID 36496397, 2022). "Early resistance to LM is dependent on NF-κB and IRF3/7 activation, subsequent production of inflammatory cytokines (TNF, type I-III interferons, etc.), and the recruitment of activated monocytes, macrophages, and neutrophils to the sites of infection." (PMID 35925892, 2022). "The application of D. dao in infection wounds increased the expression of TGF-β1 and decreased the expression of TNF-α, which were beneficial to increase collagenous fiber to form granulation tissue and accelerate epithelial regeneration during wound healing." (PMID 35783508, 2022). "Nevertheless, the utilization of iRHOM siRNA treatments in interim of infection significantly regresses TACE trafficking, TNF-α release, and TGFβRII shedding." (PMID 35585977, 2022). "Repeating mouse infection experiments at 4 hr with the D39 S. pneumoniae strain demonstrated similar BALF cytokine results, with increased TNF and reduced IL‐1β levels for mice infected with D39Δply compared to D39 or the ply complemented strain." (PMID 35835695, 2022). "The ability of TNF-primed NDAS skin fibroblasts to stabilize IKKi levels and resist infection with hPIV3 is consistent with a role for IKKi in NF-κB activation and innate antiviral immunity." (PMID 35289316, 2022). "We have previously suggested that NK cells do not have a role in the direct control of the mycobacteria growth of Mtb, however, the contact between NKs and DCs during infection by M. bovis increases the production of IFN-γ, TNF-α, CCL2, CCL4, and CXCL8." (PMID 35456728, 2022). "After infection, several additional pro-inflammatory upstream regulators including PTGS2 (COX2), IL1A, TNF, and SPI1 (PU.1) were activated at higher levels in aged mice." (PMID 35614490, 2022). "PD-1+ TOX+ CD8+ T cells isolated from the site of infection produced significantly less IFN-γ, TNF-α and Granzyme B than their PD-1- TOX- CD8+ T cell counterparts after T. cruzi-specific stimulation ex vivo." (PMID 35720419, 2022). "Treatment of infected cells with BI-605906 limited both TNF and TNFAIP3 transcriptional activation following infection." (PMID 35022513, 2022). "Several chemokines were induced quickly in the early phase (day 2 p.i.)and maintained at a rather high level through the first week of infection, including CCL2, CCL3, CCL4, CCL7, CXCL10, IL-6, IFN-γ, CCL11, CCL5, TNF-α, CXCL1, IL-4, IL-12p70." (PMID 34379705, 2021). "The expression of IL-1β, IL-6, IL-8, IL-18, TNF-α, MMP-9, RANKL, TLR-2, TLR-4, TLR-6, thymic stromal lymphopoietin (TSLP), and ICAM-1 was evaluated by qPCR at 2 and 24 h after infection." (PMID 33802988, 2021). "This is in line with our unpublished results, which demonstrate that ex vivo infection of vaginal explants with HSV-2 results in upregulation of not only IFN-λ but also several other immune factors, including CXCL9, CXCL10, IL-1α and TNF-α." (PMID 35126336, 2021). "In the immune organ head kidney, the transcripts of anti-inflammatory cytokine TGF-β induced by AHFGDS infection increased 4.7-fold (p < 0.01) comparing to ZYAH72 infection group, while pro-inflammatory cytokines TNF-α level decreased 3.8-fold (p < 0.01)." (PMID 34063680, 2021). "The lung and trachea homogenates from all animals had detectable cytokines (IL-6, IL-1α, IL-1β, TNFα and TGFβ) and chemokine (MCP-1) at Day 7 post-infection." (PMID 34452519, 2021). "The results showed that the levels of sIL-2R, TNF-α, and PCT were correlated with other laboratory indicators of infection in the two groups of patients." (PMID 34745113, 2021).